LARP6 (La ribonucleoprotein 6, translational regulator)
Description:
Regulates the coordinated translation of type I collagen alpha-1 and alpha-2 mRNAs, CO1A1 and CO1A2. Stabilizes mRNAs through high-affinity binding of a stem-loop structure in their 5' UTR. This regulation requires VIM and MYH10 filaments, and the helicase DHX9.
Synonyms: Achn; acheron; FLJ11196
Tractability: PROTAC: its protein half-life has been measured.
Gene: Protein-coding gene on chromosome 15 (70,829,130 to 70,854,157, reverse strand). Ensembl gene ENSG00000166173.
Subcellular location: Cytoplasm; Nucleus
Subcellular location (Human Protein Atlas): Microtubules; Cytokinetic bridge
Gene Ontology:
Molecular function: mRNA 5'-UTR binding; myosin binding; protein binding; RNA stem-loop binding; sequence-specific mRNA binding; nucleic acid binding; RNA binding
Biological process: positive regulation of collagen biosynthetic process; RNA processing
Cellular component: cytoplasm; nucleus; ribonucleoprotein complex
Genetic constraint (gnomAD): Loss-of-function variants: 18 observed, 27.9 expected, observed/expected ratio (o/e) 0.65, 90% interval 0.44 to 0.96. The upper end of that interval is the gene's LOEUF score, 0.96, which puts it in group 4 of 6, group 1 being the genes least tolerant of losing a copy. Missense variants: 583 observed, 614.81 expected, observed/expected ratio (o/e) 0.95, 90% interval 0.88 to 1.01. Synonymous variants: 284 observed, 244.13 expected, observed/expected ratio (o/e) 1.16, 90% interval 1.05 to 1.28.
Homologues: Orthologues: chimpanzee LARP6 (100% identical), macaque LARP6 (99% identical), pig LARP6 (94% identical), dog LARP6 (92% identical), mouse Larp6 (91% identical), guinea pig LARP6 (90% identical), rat Larp6 (90% identical), rabbit LARP6 (75% identical), tropical clawed frog larp6 (61% identical), zebrafish larp6a (55% identical), Drosophila melanogaster Larp4B (14% identical), Caenorhabditis elegans larp-5 (14% identical), and 2 more. Paralogues in human: LARP7 (19% identical), LARP1 (17% identical), LARP4B (16% identical), LARP1B (15% identical), LARP4 (15% identical), SSB (13% identical).